MET (MET proto-oncogene, receptor tyrosine kinase)
Diseases named in the same sentence as MET in open-access papers (continued):
Sharing a sentence is not in itself a finding about the gene and the disease.
tumor (continued). "Using a digital pathology method to measure the signal intensity, converting signal intensity into a digital surrogate measure of single cell transcript levels, we found a significant increase in MET transcription in budding cells compared to the central tumor regions (p < 0.001)." (PMID 27793046, 2016). "Consistent findings in vivo revealed that miR-34a induced regression of gefitinib-resistant tumours in conjunction with gefitinib intervention, an effect that could be ascribed to reduced expression of MET and phospho-EGFRTyr1068." (PMID 26891293, 2016). "In addition, binding of LY2875358 to MET results in internalization and degradation of MET, leading to suppression of ligand-independent cell proliferation and tumor growth in preclinical models where MET is constitutively activated." (PMID 27422720, 2016). "MET showed 46 mutations and they were identified either in the primary tumor or metastatic lesions, but not in both lesions, showing a 100% heterogeneous nature of mutation." (PMID 26782967, 2016). "Initial clues that coagulation may be linked to tumorigenesis comes from studies overexpressing the human oncogene MET in somatic cells of the liver, which resulted in hypercoagulation and internal haemorrhage, and correlated with tumour development." (PMID 26996437, 2016). "For example, in the phase III onartuzumab clinical trial, defining IHC MET positivity as 50% of tumor cells with moderate staining intensity might have resulted in the inclusion of patients with false-positive MET-overexpressing tumors." (PMID 27013592, 2016). "Since it has been reported that cancer-associated mesothelial cells that colonize the peritoneum produce fibronectin, able to trap HGF produced by the fibroblasts of the tumor microenvironment, the inhibition of c-MET activation seems to be a promising target to block cancer metastasis." (PMID 27563880, 2016). "One noticeable difference in the killing of the afatinib H1975 tumor cells between [siERBB3 + si-c-MET + si-c-KIT] and [dasatinib + afatinib] was the relative impact of blocking autophagosome formation and of blocking eIF2α-dependent endoplasmic reticulum stress signaling." (PMID 26934000, 2016). "In addition to inhibiting tumors with MET gene amplification, ABT-700 also inhibits the subcutaneous xenograft growth of human tumor cell lines that have c-Met protein overexpression or autocrine HGF." (PMID 26879245, 2016). "The combination of HER2, CAIX, GLUT1, EGFR, IGF1-R and MET could detect 45.5 % of tumours, including basal/triple negative and HER2-driven ductal cancer." (PMID 26860296, 2016). "In Patient #1, c-MET amplification was shown by exome sequencing, and there was evidence that downstream activation of related pathways contributed to the growth of this patient's tumor." (PMID 26510912, 2015). "Consequently, patients' selection in the ongoing phase 3 METIV-HCC trial of tivantinib is based on the detection of high expression of c-MET in tumor biopsies." (PMID 26259250, 2015). "A more recent type of population enriched design ignores traditional tumor histologic origin and classification (eg, gastric, lung etc.)by enriching for a certain biomarker, such as PIK3CA mutation or MET amplification, irrespective of tumor histology." (PMID 25557400, 2015). "Over expression of c-MET in such tumours is claimed to be related to increased tumour cell motility, invasiveness, and angiogenesis which may stimulate tumour metastatic ability and contribute to tumour aggressiveness." (PMID 26459369, 2015). "Furthermore, MET inhibition demonstrated an efficient anti-tumor activity and considerable reduction in microvessel density only against the M1268T-derived intrahepatic tumors." (PMID 26413215, 2015). "Similar to MET, RON is also implicated in tumor invasion and metastasis." (PMID 26528757, 2015). "We found that MET silencing in HTB-35 cells dramatically decreased tumor growth." (PMID 25888626, 2015).
tumor (continued). "We determined EGFR and c-MET expression levels on a panel of 11 tumor cell lines using QFCM." (PMID 26260789, 2015). "In this work, we focus on the tumour cells characterised by CD44, CD47 and MET mutations." (PMID 25978366, 2015). "Heterogeneity of MET staining pattern among different tumor cores was also observed." (PMID 26041880, 2015). "The simultaneous targeting of both signaling pathways with an EGFR x c-MET bispecific antibody (BsAb) could produce synergies that more effectively block tumor proliferation and metastasis (21, –, 23)." (PMID 26260789, 2015). "They found that tivantinib indiscriminately caused cell death on all actively mitotic tumor cells, regardless of MET gene copy number and MET protein expression." (PMID 26123926, 2015). "Notably, the two highly amplified tumors were immunonegative (scores 0 and 1+), whereas the only tumor with intermediate MET gene copy level reached an immunoscore 2+." (PMID 25844809, 2015). "Furthermore, numerous studies have suggested that MACC1 induces tumor metastasis through the regulation of the hepatocyte growth factor (HGF)/MET signaling pathway." (PMID 26043756, 2015). "In HCC, MET overexpression has been reported in 20-48% of tumor samples compared to peritumoral normal tissue and was further correlated with clinicopathological features of these tumors such as presence of multiple nodular tumors and association with high proliferative index." (PMID 26413215, 2015). "As with many growth factor receptors, the actions of MET are co-opted during tumor growth." (PMID 25605252, 2015). "Consequently, in the current study we aimed to investigate the impact of aberrant MET activity targeting on pro-angiogenic activities in MET-driven tumor cells and in a liver xenograft model." (PMID 26413215, 2015). "MET protein expression levels in tumor tissues may be prognostic biomarkers of survival in selected cancer types." (PMID 28536405, 2015). "Concerning the 209 tumor tissues evaluated for MET expression, percentage acounts 3.8 %." (PMID 26215852, 2015). "Inhibiting activation of c-MET in cancer cells, in combination with other approaches for reducing desmoplasia in the tumor microenvironment, might significantly improve the success of chemotherapy." (PMID 26404380, 2015). "Tumour c-MET expression was also predictive of response to tivantinib." (PMID 28943627, 2015). "We previously reported that selective MET inhibitors may specifically inhibit HGF-autocrine GBM tumor growth." (PMID 26381735, 2015). "Moreover, the expression levels of the sf-RON in the tumor tissues significantly increased compared with those in adjacent non-tumor tissues, especially in MET+ samples (p = 0.0017)." (PMID 26528757, 2015). "Rather than using a ‘one size fits all’ approach however, we propose first that a biomarker such as high HGF concentrations in ascites, or high c-MET/phosphorylated c-MET in tumour samples, be used to select patients for therapy with small molecule c-MET inhibitors." (PMID 26138303, 2015). "However, upon disease progression on EGFR TKI therapy, a striking increase in MET activation was observed in tumor cells from patient 006-010, possibly reflecting a compensatory mechanism for tumor growth." (PMID 26439803, 2015). "Importantly, matched tumor samples from patients before and after treatment with tivantinib demonstrate MET inhibition." (PMID 26413215, 2015). "MET amplification was found at low levels in tumor tissues before treatment." (PMID 26318427, 2015). "It seems that, in these cases, a greater concentration of HGF and/or proximal interaction of tumor and stromal cells are critical for the activation of the MET pathway (although HGF measurements include the stromal pool, and thus they do not necessarily equate with its active form)." (PMID 26319934, 2015).
tumor (continued). "The result of using human and mouse arrays to identify the core pathways affected by MET inhibitors in the context of tumor/host crosstalk is speculative but very promising." (PMID 26381735, 2015). "In vivo, we could demonstrate that MET inhibition was bound to a decrease in the size and in the vascularization of tumor in a murine liver xenograft model." (PMID 26413215, 2015). "Increased chemotaxis of the tumor cells with activated MET signaling may be relevant to RMS metastasis in patients." (PMID 26384300, 2015). "A few NSCLC tissue samples (11 tumor samples are shown) could be selected for the comparison of MET expression levels evaluated on protein level by IHC and western blot analysis and on mRNA-level by real-time PCR." (PMID 26215852, 2015). "Also a tumor-suppressive function of miR-199a, being pro-apoptotic by targeting the MET proto-oncogene and its downstream effector ERK2, was demonstrated in fibroblasts." (PMID 26251897, 2015). "Tumour cells may also potentiate pro-metastatic c-MET signalling via an autocrine mechanism involving TIMP-1, leading to downstream expression of metastasis-promoting genes." (PMID 26013123, 2015). "The phenomenon of HGF/MET-induced bypass is in line with previous reports in other tumor types." (PMID 26496080, 2015). "To determine whether responsive tumors may belong to the late TGF-beta signature subgroup we assessed the expression of c-MET at baseline, Vimentin being detected at similar levels across all control tumor samples." (PMID 26057634, 2015). "Through a siRNA library screening that targeted most genes encoding RTKs and subsequent validation, we found that knockdown of 4 RTK receptors (FGFR2, RON, EPHA1, and RYK) via siRNA sensitized MET-addicted tumor cells to PF, while b-FGF-induced activation of FGFR2 conferred resistance to the PF." (PMID 26528757, 2015). "Finally, HGF plays an important role on tumor microenvironment, e.g., acting on MET-expressing endothelial cells and thereby stimulating tumor angiogenesis." (PMID 28548076, 2014). "However, it is likely that the requirement for RAS pathway activation for tumor development and progression in humans is achieved in the mouse through the activation of c-MET by HGF over-expression." (PMID 25329316, 2014). "c-MET protein was observed in 61 cases (57%) at the tumor cell level." (PMID 24465403, 2014). "In this study, we show that the combination of a selective MEK inhibitor and a PI3K/mTOR inhibitor is effective against tumor cell lines refractory to gefitinib by three different mechanisms: an EGFR gatekeeper T790M mutation, MET amplification, and KRAS/PIK3CA mutation." (PMID 24939055, 2014). "In the third experiment, we tested whether MET inhibition could prevent tumor cell dissemination out of small primary tumor sites." (PMID 25162504, 2014). "Therefore, the elevated c-MET expression likely acted as a survival factor for the tumor cells treated with a combination of erlotinib and radiation, and the blockade of c-MET signaling significantly enhanced the tumor cytotoxicity effects." (PMID 25505849, 2014). "Conversely, they may behave as antagonists, inhibiting MET-mediated uncontrolled excessive responses of tumor cells." (PMID 28548076, 2014). "Because microRNAs are naturally existing small molecules and target multiple genes, overexpression of miR-608 or miR-34a could exert greater anti-tumor effects than EGFR or MET inhibitions." (PMID 24621885, 2014). "Therefore, HGF/SF typically activates MET in a paracrine fashion, although in some cancers the tumor cells themselves express HGF/SF, which leads to an autocrine loop-type mechanism for MET activation." (PMID 25268161, 2014). "Similarly, hepatocyte growth factor (HGF) and c-MET play important roles in the control of tumor growth, invasion and metastasis." (PMID 25162296, 2014).
tumor (continued). "Like HER2 amplification and KRAS mutations, rare MET-amplified cells were found in pretreatment tumor material from one out of three patients with MET-driven acquired resistance, suggesting that preexisting clones were selected under the pressure of anti-EGFR therapy." (PMID 24811491, 2014). "DN-30 Fab (also called monovalent DN-30, MvDN30) reduces the anchorage-independent growth of a broad panel of HGF-dependent or -independent tumor cells, and induces growth arrest and apoptosis of tumor cells addicted to MET signaling in in vitro proliferation assays." (PMID 28548076, 2014). "Cabozantinib (XL-184, Exelixis, South San Francisco, CA) is a small compound tyrosine kinase inhibitor of VEGFR2, c-MET and RET and has been shown to block tumor development in the RipTAG2 mouse model of pancreatic carcinogenesis more effectively than blockade of c-MET or VEGFR2 alone." (PMID 23484006, 2013). "To investigate whether the remaining diffuse infiltrative tumor might be the result of incomplete c-MET inhibition, we prepared tumor extracts from treated and control animal brains and prepared Western blots." (PMID 23484006, 2013). "Strikingly, NK4 inhibits tumor angiogenesis through a MET-independent pathway." (PMID 23296269, 2013). "According to this hypothesis, inhibition of VEGF-A releases PTP1B from the multi-receptor complex, unleashing c-MET and resulting in increased diffuse infiltrative tumor growth." (PMID 23484006, 2013). "IHC using the phospho-specific anti-c-MET antibody also confirmed the presence of activated c-MET, although in a heterogeneous fashion, being present predominantly in diffuse infiltrating tumor cells in the corpus callosum and adjacent white matter (arrow and 1F)." (PMID 23484006, 2013). "Angiogenesis inhibition has not yielded significant advances in the treatment of CRPC to date, and a growing body of evidence suggests that signaling through MET may be a compensatory mechanism by which tumor cells escape anti-angiogenic therapy." (PMID 24205338, 2013). "Even in cases of MET mutation, HGF is important for tumor malignancy." (PMID 23296269, 2013). "In the current study, FGFR1 and MET amplifications were restricted to the EGFRwt/KRASwt tumor group, and were mutually exclusive (MET amplification was borderline non-significant for difference in frequency between mutation groups, p=0.09, Fisher’s exact test)." (PMID 24205279, 2013). "When rat HGF cDNA was introduced into immortalized mouse liver epithelial cells (MLE10), all MLE10-HGF cell lines grew much faster than the original MLE10 cells in culture and produced in large colonies in soft agar, suggesting the involvement of aberrant MET signals in tumor onsets." (PMID 23296269, 2013). "Cabozantinib has better effects on tumor angiogenesis and survival than those found with combinations of selective inhibitors of MET and VEGF signaling in the same model, suggesting that AXL or other targets (such as RET, KIT and TIE2) contribute to the efficacy of cabozantinib." (PMID 24213559, 2013). "Indeed, the activation of HGFR/c-MET has been reported to trigger cancer cell proliferation, migration and invasion and to promote tumor vessel angiogenesis, since HGF directly stimulates endothelial cell proliferation and migration." (PMID 22606042, 2012). "MET activity is a key promoter of the invasive growth program in tumor cells." (PMID 22807917, 2012). "MET gene mutation is not a frequent initiating event in most common human cancers, but it was more frequently associated with tumor progression." (PMID 23320251, 2012). "The tumor microenviroment can secrete growth factors such as hepatocyte growth factor (HGF) which results in activation of the HGF receptor MET and subsequent downstream Raf/MEK/ERK and PI3K/PTEN/Akt/mTOR signaling which results in resistance to the small molecule inhibitors." (PMID 23085539, 2012).
tumor (continued). "In vivo administration of a c-MET inhibitor indeed prevented the formation of metastases and decreased pancreatic xenograft growth, while combined treatment with gemcitabine completely stalled tumor growth." (PMID 24213498, 2012). "Changes in the MET gene involve ligand-independent activation of the intracytoplasmic tyrosine kinase domain leading to activation of the hepatocyte growth factor (HGF)/MET pathway resulting in tumor formation." (PMID 22312516, 2011). "Unsupervised clustering of the mouse and human samples showed a relationship between a subset of human HCC profiles and the mouse tumor samples, indicating that the c-MET mouse may be a useful model for studying HCC patients with activated Wnt signaling." (PMID 21949730, 2011). "Knock-down of c-MET further strongly reduced tumour-formation in nude mice." (PMID 22110593, 2011). "Significant reduction of tumour formation occurred in the DU145 clones with silenced c-MET." (PMID 22110593, 2011). "MET is a receptor tyrosine kinase (RTK) whose gene is amplified in various tumour types." (PMID 21847121, 2011). "Finally, given that both the adjacent and the distant tissues also express the c-MET transgene, we included the wild-type vs. tumor signature to identify any c-MET-driven gene expression changes." (PMID 21949730, 2011). "Interestingly, amplification of the MET gene (>10 copies per cell) is present only in 3 of 23 (13%) tumor tissues." (PMID 21776391, 2011). "MET silencing strongly delayed tumor onset in mice injected with control cells." (PMID 20500904, 2010). "Thus, MET is considered a good candidate for targeted therapeutic intervention in this type of tumor, and MET inhibitors recently entered clinical trials." (PMID 20500904, 2010). "Tumors with MET and NRAS mutations also have an unexpectedly high frequency of co-occurring mutations, which suggests that they occur as a second mutation and perhaps later in the etiology of the tumor." (PMID 20233444, 2010). "However, tumors expressing EGFR-L858R or having the TGFα autocrine production were considerably resistant to MET silencing, as demonstrated by a complete rescue in tumor incidence." (PMID 20500904, 2010). "The MET protein was expressed in 14 out of 33 tumor samples (42%)." (PMID 20066159, 2009). "Furthermore, in cells expressing TFE3, inhibition of MET using siRNA or a small molecule MET inhibitor impaired tumor growth." (PMID 19146682, 2009). "Resistance in one-quarter of the specimens could be attributed to amplification of the oncogene MET, implying that alternative routes to resistance must exist that confer comparable fitness advantages to these tumor cells." (PMID 19079573, 2008). "Finally, MET mRNA levels were significantly increased (P = 0.016) in tumor grade III samples compared with grade I + II samples." (PMID 18928543, 2008). "It is known that NSCLC patients with EGFR-dependent primary tumours when treated with TKIs can develop metastases, in which either the EGFR signalling is negated or resistance is acquired due to secondary EGFR mutations like T790M or MET amplification." (PMID 19238633, 2008). "We validated this assay through assessment of MET inhibitor-treated preclinical models, peptide blocking experiments to demonstrate specificity, and concordance with corresponding measurements from the same specimens using a previously validated sandwich immunoassay of tumor lysates." (PMID 42118765, 2026). "Instead, c-MET protein upregulation may occur due to transcriptional mechanisms or post-transcriptional modifications, often following the activation of other driver genes that contribute to tumour progression." (PMID 40078386, 2025).